NOTCH1 (notch receptor 1)
Diseases named in the same sentence as NOTCH1 in open-access papers (continued):
Sharing a sentence is not in itself a finding about the gene and the disease.
colitis (6 papers, 2020 to 2024). Inflammation of the colon. "In addition, the mRNA expression of Notch1 and Hes1 was assessed in different H. pylori–associated gastrointestinal diseases including gastritis, duodenal ulcer, gastritis with duodenal ulcer, and gastritis with colitis." (PMID 33224898, 2020). "To further confirm whether NOTCH1 is essential for OLFM4 to regulate colitis, we inhibited the Notch signaling pathway by DAPT47." (PMID 37151883, 2023). "However, the expression of Notch1 in the gastritis with colitis group, which involves inflammation of the upper and lower gastrointestinal tract, was significantly higher compared with that in the upper gastrointestinal tract inflammation group." (PMID 33224898, 2020). "Notably, the expression of Notch1 was upregulated in the gastritis with colitis group when compared with the upper gastrointestinal tract inflammation group." (PMID 33224898, 2020). "In addition, Notch1 expression in the gastritis with colitis patients was higher than that in the gastritis with duodenal ulcer patients." (PMID 33224898, 2020). "Thus, mRNA expression of Notch1 and Hes1 was examined in the CD4+ T cells from patients with different H. pylori–associated gastrointestinal tract inflammation including gastritis, duodenal ulcer, gastritis with duodenal ulcer, and gastritis with colitis." (PMID 33224898, 2020). "Using both murine and human models of colitis, we demonstrate that loss of epithelial but not stromal DCLK1 synergizes with stromal Notch1 to regulate inflammatory processes in the colon." (PMID 34226497, 2021). "When intestinal epithelial cell-specific Dclk1-knockout (Dclk1ΔIEC) or Dclk1ΔIEC;Rag1−/− double knockout (DKO) mice were infected with CR and given a single dose of DBZ, they developed barrier defect and severe colitis with higher levels of stromal DCLK1-S, Ly6G, NE, and Notch1." (PMID 34226497, 2021).
colon adenocarcinoma (6 papers, 2014 to 2024). "It is associated to histological type (p = 0.00173) and NOTCH1 is overexpressed in 73.2% of colon adenocarcinoma, 59.7% of colon mucinous adenocarcinoma, 84.4% of rectal adenocarcinoma and 76.9% of rectal mucinous adenocarcinoma." (PMID 30380753, 2018). "Furthermore, in human colon adenocarcinoma cell lines, Notch1 plays a role in chemotherapeutic (Oxaliplatin) resistance, as Notch1 expression was found to be upregulated in a dose dependent manner." (PMID 32796631, 2020).
cyst (6 papers, 2012 to 2023). A sac-like closed membranous structure that may be empty or contain fluid or amorphous material. "In another study, ablation of Notch1 in K14-expressing tissue led to the formation of cyst-like structures replacing the MGs50." (PMID 36932132, 2023). "The results revealed that the Notch1 intracellular domain (N1ICD) was upregulated in the cyst-lining epithelial cells of P7 cpk mutants compared to control non-cystic littermates." (PMID 29463793, 2018). "In order to examine the effect of Notch1 deletion on cyst formation, we utilized PDX-1-Cre;Notch1lox/lox mice, which allow for conditional deletion of Notch1lox/lox alleles specifically in pancreatic epithelial cells at day 8.5 of embryonic development." (PMID 23284900, 2012). "Interestingly, when comparing the basal and parabasal layers of OKC, we observed predominant staining of NOTCH1 and HIF-1α in the epithelial layers near to the cyst lumen." (PMID 31319505, 2019).
Ewing sarcoma (6 papers, 2014 to 2025). A small round cell tumor that lacks morphologic, immunohistochemical, and electron microscopic evidence of neuroectodermal differentiation. "Another example of functionally inactive NOTCH1 with uncoupling HES1 expression was evidenced by cytoplasmic staining in Ewing's sarcoma." (PMID 40387567, 2025). "Moreover, some studies have also indicated that PIK3R1, NOTCH1, and CREBBP are common in recurrent Ewing sarcoma." (PMID 36964542, 2023). "Induction of differentiation in tumor cells could be triggered by down regulation of Notch-1 and ID2, both of which were indeed down regulated very clearly due to combination of EWS shRNA plasmid transfection and TFL treatment in Ewing’s sarcoma SK-N-MC and RD-ES xenografts." (PMID 27547487, 2014).
Hodgkins lymphoma (6 papers, 2005 to 2020). A heterogeneous group of malignant lymphoid neoplasms of B-cell origin characterized histologically by the presence of Hodgkin and Reed-Sternberg (HRS) cells in the vast majority of cases. "Usually, NOTCH1 is repressed by PAX5; however, aberrant expression of NOTCH1 interferes with the B lymphoid phenotype of neoplastic B cells in the classical Hodgkin lymphoma." (PMID 32604737, 2020). "Studies have indicated that Notch1 and Jagged1 are highly expressed in B- and T-cell-derived Hodgkin's lymphoma and anaplastic large cell tumor cells." (PMID 26339248, 2015). "The Hodgkin's lymphoma cell line L540 served as positive control for Notch 1-EC expression and in vitro translated mHESl cDNA for HES1 protein expression." (PMID 16136053, 2005). "NOTCH1 expression was detected in 78.1% (25/32) of EBV-positive cases, nodular sclerosis being the most frequent subtype (11/25, 44%)." (PMID 32604737, 2020).
Infertility (6 papers, 2019 to 2025). "As reported in previous literature, aberrant activation of canonical Notch1 signaling in the mouse uterus could decrease the level of progesterone receptor by hypermethylation that can lead to infertility." (PMID 36776897, 2023). "Furthermore, it has been identified that Jagged1, Jagged2, DLL1 and Notch Receptor 1 (NOTCH1) expression are significantly lower at the mid-secretory phase in women with infertility, compared to fertile subjects." (PMID 33773601, 2021). "A recent study has revealed that NOTCH1 and NOTCH ligands including JAG1 and DLL1 are down-regulated in the endometrium of women with unexplained infertility during the implantation window compared with the fertile subjects." (PMID 31168348, 2019).
neuroendocrine tumor (6 papers, 2017 to 2023). "The researchers’ primary goal was to demonstrate that resveratrol treatment in patients with low-grade GI neuroendocrine tumors will significantly increase Notch1 activation in post-treatment tumor biopsy specimens when compared to pretreatment levels." (PMID 37111115, 2023). "A study conducted by the University of Wisconsin, aimed to investigate the effects of resveratrol and Notch-1 on neuroendocrine tumor tissue patients with neuroendocrine tumors, assessed how well they tolerated the product when taken for up to three months." (PMID 37111115, 2023). "For example, VPA upregulated Notch1 expression, inhibited cell cycle, and induced of apoptosis, both in vitro and in vivo, as well as suppressed expression of the neuroendocrine tumor markers." (PMID 34068438, 2021). "Although in many cancer types Notch1 is an important tumor promoting oncogene, it was shown to possess a tumor suppressive effect in some hematopoietic cancers and especially in neuroendocrine tumors such as MTC." (PMID 28122586, 2017). "However, in MiNEN (mixed neuroendocrine/non neuroendocrine neoplasm), the expression of NOTCH1 and Hes1 is reduced or absent in the neuroendocrine cells, but both NOTCH1 and Hes1 are present in the adenomatous component, potentially indicating a possible role of NOTCH as a tumour suppressor gene." (PMID 31443481, 2019).
serous ovarian cancer (6 papers, 2014 to 2024). "In this study, we performed in silico analyses using The Cancer Genome Atlas data to discover novel Notch-related lncRNAs and validated our transcriptome data via NOTCH1/3 silencing in serous ovarian cancer cells." (PMID 35326706, 2022).
splenic marginal zone lymphoma (6 papers, 2016 to 2025). Splenic marginal zone lymphoma is a rare, indolent B-cell non-Hodgkin lymphoma characterized by abnormal clonal proliferation of mature B-lymphocytes with involvement in the spleen, bone marrow and, frequently, the blood. "Similarly, mutations in the NOTCH1 pathway correlate with shorter overall survival and increased risk of histologic transformation, particularly in CLL, MCL, and splenic marginal zone lymphoma (SMZL)." (PMID 40150070, 2025).
viral infection (6 papers, 2012 to 2024). "Other diseases are linked to nearly every major system of our body and inflammatory response, consistent with the important role of Notch1 signaling in development, homeostasis, and viral infection." (PMID 38043798, 2024). "CD22 blockade was sufficient to inhibit the immune dysregulation triggered by Notch1 signaling in Tregs in the poly I:C proxy viral infection model, highlighting the critical role of this molecule in MIS-C disease pathogenesis." (PMID 36282598, 2023). "This work provides evidence that some host lncRNAs promote PFV replication by outweighing NOTCH1 inhibition during early viral infection." (PMID 37628760, 2023). "This experiment confirmed that siNotch1 effectively interferes with Notch1 expression, whereas expression is unaffected by viral infection alone." (PMID 22937170, 2012). "There is also evidence that lncRNAs regulate Notch1 signalling during viral infection." (PMID 37628760, 2023). "This may be related to enhanced viral replication; it may be worthwhile exploring the interaction between Notch1 signalling and virus infection control in future." (PMID 22937170, 2012). "In the context of viral infection, JAG1/Notch 1 signaling participates in the development of Th2 response in bronchial epithelial cells following infection with respiratory syncytial infection." (PMID 33883570, 2021). "Moreover, in mice either expressing an active form of Notch1 in Tregs (Foxp3EGFPCreR26N1c/+) or lacking NUMB expression in these cells (Foxp3EGFPCreNumbΔ/Δ), treatment with polyinosinic:polycytidylic acid (poly I:C) to simulate viral infection induced systemic inflammation." (PMID 36282598, 2023).
abdominal aortic aneurysm (5 papers, 2017 to 2021). Enlargement and ballooning of the vessel that supplies arterial blood to the abdomen, pelvis and legs. "Previously, we demonstrated that Notch1 deficiency promotes Tgf-β2 dependent M2-polarization in a mouse model of abdominal aortic aneurysm." (PMID 31142802, 2019). "The inflammatory response mediated by Notch1 signaling pathway stabilizes the progression of small abdominal aortic aneurysm induced by angiotensin II (AngII)." (PMID 33535178, 2021). "The Notch1-mediated inflammatory response participates in the development of abdominal aortic aneurysm (AAA)." (PMID 33535178, 2021). "Plasma Notch1 and tumor necrosis factor-α converting enzyme (TACE) levels were significantly higher in the abdominal aortic aneurysm (AAA) postulating that the Notch1 signaling in macrophages plays an important role in AAA development and progression." (PMID 31770379, 2019).
adenomyosis (5 papers, 2015 to 2025). The growth of endometrial tissue inside the muscular wall of the uterine corpus. "In mouse models, it has been revealed that there is an increased levels of EMT markers and Notch 1 activation during the development of adenomyosis when compared to the control sample." (PMID 38791461, 2024). "In the current study, elevated Notch1 expression was noted in adenomyosis, suggesting its significant role in this disease." (PMID 26307032, 2015). "We conclude that Notch1/Numb/Snail signaling plays an important role in the pathogenesis and development of adenomyosis." (PMID 26307032, 2015). "In our next study, our team will examine the involvement of Notch1 signaling in adenomyosis using multiple experimental techniques." (PMID 26307032, 2015). "In the current study, we aimed to investigate the status of Notch1/Numb/Snail signaling in adenomyosis and to explore the possible role of this signaling pathway in the development and progression of this disease." (PMID 26307032, 2015). "In ectopic endometria of adenomyosis, the immunostaining of Notch1 was strongly positive and was also restricted to the cytoplasm of epithelial cells; weak immunostaining was observed in stromal cells." (PMID 26307032, 2015). "In conclusion, our data demonstrate the possible involvement of Notch1/Snail/Numb signaling in the pathogenesis and development of adenomyosis." (PMID 26307032, 2015). "In the current study, we found that the EMT-related Notch1/Numb/Snail signaling pathway plays an important role in the pathogenesis of adenomyosis." (PMID 26307032, 2015). "However, ectopic endometria of adenomyosis in both the proliferative and secretory phases showed significantly increased Notch1 expression compared to normal endometria (p < 0.01)." (PMID 26307032, 2015). "The current study may provide new insight into the diagnosis and treatment of adenomyosis.However, the main limitation of this study is that we only examined the expression and location of Notch1/Numb/Snail signaling by immunohistochemistry." (PMID 26307032, 2015). "The objective of this study was to explore Notch1/Numb/Snail signaling in adenomyosis." (PMID 26307032, 2015). "We found that the expressions of Notch1 and the EMT-related proteins N-cadherin, Snail and Slug were upregulated in the ectopic endometrium of adenomyosis compared with normal endometrium." (PMID 26307032, 2015).
Arthritis (5 papers, 2021 to 2023). Inflammation of a joint. "In a mouse model of antibody-mediated arthritis induced by transfer of K/BxN mouse serum, Notch3-deficient mice were resistant to arthritis induction and anti-Notch3 neutralizing antibodies blunted disease severity (with lesser effects for anti-Notch1 antibodies)." (PMID 34124039, 2021). "Antibody-mediated inhibition of Notch1 signaling by an IgG1 anti-human and anti-mouse Notch1 led to a modest attenuation in arthritis severity and paw swelling." (PMID 33912195, 2021). "Notch1 signaling and the corresponding effector genes act as important roles in prevention of inflammation and oxidative stress in numerous human diseases, such as arthritis, enteritis, myocardial injury, and chronic obstructive pulmonary disease." (PMID 34961513, 2021). "In a rat CIA model, a NOTCH1 and NOTCH3 inhibitor (LY411575) showed therapeutic effect of arthritis, presumably by inducing fibroblast death since LY411575 is able to induce death of human synovium derived fibroblast cell line, MH7A in vitro." (PMID 35252279, 2022). "Genetically engineered Notch1 Antisense-expressing (NAS) mice, where global expression of Notch1 is reduced, are less arthritogenic than controls, while conditional myeloid overexpression of NICD1 trended towards worsened arthritis in one study." (PMID 33912195, 2021).
brain injury (5 papers, 2016 to 2025). Acute and chronic (see also brain INJURIES, CHRONIC) injuries to the brain, including the cerebral hemispheres, CEREBELLUM, and brain STEM. "Related investigations have also found that the levels of Notch1 protein and mRNA are down-regulated in injured tissue, but are then gradually upregulated to the normal levels in the early stage of traumatic brain injury." (PMID 35383529, 2022). "Thus, treatment methods that activate Notch1 may be beneficial in acute brain injuries by protecting BBB integrity." (PMID 36028880, 2022).
cardiomyopathy (5 papers, 2020 to 2024). A disease of the heart muscle or myocardium proper. "Second, given the broad inclusion criteria for the CGC study from which many families were ascertained (which includes CHD, in addition to aortopathy, cardiomyopathy, and arrhythmias), commenting on the prevalence of NOTCH1 variants in CHD is beyond the scope of this paper." (PMID 38778082, 2024). "So, we can raise the hypothesis that a down expression of NOTCH1 in CCC patients promote the Th1 response associated to severe cardiomyopathy." (PMID 36072583, 2022). "We identified further genes that regulate the development of trabeculation (NKX2-5, TBX20, HAND2, NRG1, NOTCH1 and DTNA) and those with evidence of involvement in cardiomyopathies (CRYAB and RIT1 (ARHGEF2))." (PMID 39567769, 2024).
Cognitive impairment (5 papers, 2017 to 2026). Abnormal cognition is characterized by deficits in thinking, reasoning, or remembering. "In APP/PS1 transgenic mice, upregulation of Notch1 and Hes1 alleviates cognitive impairment." (PMID 41596253, 2026). "The findings indicated that baicalein mitigated cognitive impairment, promoted angiogenesis and suppressed neuroinflammation and apoptosis by regulating the SIRT1-mediated Notch1 pathway." (PMID 40290868, 2025). "In summary, our results identified that agomelatine could improve cognitive impairment and ameliorate AD-like pathology in APP/PS1 mice via activating DHCR24 signaling and inhibiting Akt/mTOR and Hes1/Notch1 signaling pathway." (PMID 35153715, 2021).
cutaneous melanoma (5 papers, 2014 to 2025). A primary melanoma arising from atypical melanocytes in the skin. "We recently demonstrated that Notch1 blockade with a neutralizing antibody we developed, led to reduced cutaneous melanoma cell growth and survival and importantly, reduced tumor growth, and enhanced responses to anti-PD1." (PMID 40437523, 2025). "Notch1 signaling is up-regulated in over 60% of cutaneous melanomas where it is involved in several hallmarks of cancer including growth, progression, survival." (PMID 40437523, 2025). "In cutaneous melanoma, it has been found that Notch1 promotes tumor progression by activating MAPK and Akt pathways, which have been linked to cellular invasion and metastatic spread in different tumor types." (PMID 25166211, 2014). "Notch1 seems to be increasingly important, especially in cutaneous melanoma." (PMID 31212986, 2019).
ductal carcinoma in situ (5 papers, 2009 to 2021). "Clinical experimentation work on normal breast tissue and ductal carcinoma in situ (DCIS) revealed the expression of Notch-1 and Notch-4 receptors in the tumor tissues." (PMID 30111989, 2018).